APP (amyloid beta precursor protein)
Diseases named in the same sentence as APP in open-access papers (continued):
Sharing a sentence is not in itself a finding about the gene and the disease.
multiple sclerosis (19 papers, 2014 to 2025). A progressive autoimmune disorder affecting the central nervous system resulting in demyelination. "While her original diagnosis was multiple sclerosis, we performed a full instrumental and genetic assessment, though which we identified multiple genetic variants, including a novel variant of the APP gene." (PMID 37434948, 2023). "While her original diagnosis was multiple sclerosis, we performed a full instrumental and genetic assessement, though which we identified multiple genetic variants, including a novel variant of the APP gene." (PMID 37434948, 2023). "Furthermore, we also found that the oligodendrocyte-specific gene transcript marker Mog, which was elevated in Arg1 deficient APP mice in this study, was previously identified as a critical CNS-specific autoantigen responsible for demyelination in multiple sclerosis." (PMID 34046031, 2021). "DR6 has been reported to bind the amyloid precursor protein (APP) but interactions with other ligands are unknown, despite a role in animal models of multiple sclerosis." (PMID 38106879, 2023). "In addition, APP‐positive axonal profiles enwrapped by myelin sheaths were found in early remyelinating multiple sclerosis lesions as well as during remyelination in our experimental models." (PMID 28560740, 2017). "These tracers bind extensively to white matter, which suggests that they may be useful in studies of multiple sclerosis (MS), and that proteins resulting from proteolytic processing of the amyloid precursor protein (APP) may contribute to MS." (PMID 27065425, 2016). "Moreover, using amyloid precursor protein (APP) as a marker, acute and massive axonal damage is observed during the stage of active demyelination in multiple sclerosis (MS)." (PMID 25255088, 2014).
cognitive (18 papers, 2017 to 2025). "As our previous study showed an enhanced spatial memory in NP65-deficient mice, Thus, we wondered whether NP65 deficiency could attenuate the cognitive deficits in APP/PS1 mice." (PMID 37213217, 2023). "These mice recapitulate several AD-related pathologies, including increased hydrolysis of APP, cerebral amyloid deposition, synaptic loss, and microgliosis and astrocytosis, but generally lack tau protein-associated neurofibrillary tangles and cognitive dysfunction until very advanced ages." (PMID 40305318, 2025). "Following the strategy used to develop APP KI mice, a research group has successfully developed an APP KI rat model that exhibits typical Aβ plaque deposition, microglial activation, gliosis, synaptic damage, and cognitive dysfunction." (PMID 40305318, 2025). "Selective knockdown of Tn‐R within the perforant pathway reduces APP splicing intermediates and diminishes Aβ production, thereby ameliorating cognitive deficits in APP/PS1 mice." (PMID 40891036, 2025). "The results demonstrate that T0 treatment significantly ameliorates cognitive deficits seen in APP/E4/Abca1+/- mice, as examined by Novel Object Recognition and Contextual Fear Conditioning paradigms." (PMID 28241068, 2017). "The present study demonstrates early-onset cognitive deficits of contextual fear conditioning in an AD mouse model expressing the human mutant APP and PS2 transgenes (PS2Tg2576 mice)." (PMID 29333315, 2017). "PhGs attenuated the cognitive dysfunction features of the APP/PSI transgenic gene." (PMID 33532488, 2021). "The Morris water maze test demonstrated the effect of FSS on cognitive deficit in APP/PS1 mice." (PMID 31316576, 2019). "Further studies have shown that APP/PS1 mice display beneficial changes in the intestinal flora and SCFAs following fecal transplantation and, more importantly, delay the onset of cognition deficits." (PMID 36890624, 2023). "The histone deacetylase inhibitor trichostatin A increased albumin expression and Aβ clearance in APP/PS1 mice and improved cognitive deficits." (PMID 35295737, 2021).
metabolic syndrome (17 papers, 2010 to 2025). A cluster of metabolic risk factors for CARDIOVASCULAR DISEASES and TYPE 2 DIABETES MELLITUS. "It should be noted that cholesterol, the content of which is associated with obesity and metabolic syndrome, has a high affinity for APP and Aβ." (PMID 36138973, 2022). "In conclusion, nonalcoholic steatohepatitis with its health complications including dyslipidemia, cholesterol impairments, oxidative stress, and upregulation of AChE with amyloid precursor protein (APP) are considered potential dangerous risk factors for neurotoxicity." (PMID 26576191, 2015). "AD pathological phenotype might predispose APP/PS1 mice to HFD-mediated metabolic syndrome." (PMID 33291072, 2020). "Of interest, cerebral vascular alterations induced by metabolic syndrome triggers the development of AD neuropathology by increasing the expression of APP." (PMID 39644152, 2024). "Meanwhile, in a rat model of sucrose-induced metabolic syndrome (MetS), activated oxidative stress was found to promote the synthesis of amyloid precursor protein (APP) and Aβ by increasing the activity of β-site APP cleaving enzyme 1 (BACE-1)." (PMID 38327496, 2024). "Akkermansia has been reported to promote Aβ40-42 reduction and improve intestinal barrier dysfunction and dyslipidemia in APP/PS1 mice." (PMID 37095548, 2023). "The molecular mechanisms underlying the effect of adipose tissue hypertrophy on neurodegeneration processes are related to APP production in adipose tissue in the metabolic syndrome increases, as well as levels of Aβ and cholesterol in the blood serum." (PMID 36138973, 2022). "Notably, exaggerated pro‐inflammatory cytokines in metabolic syndrome induces the formation of Aβ by triggering the expression of APP gene in PSV2UTR‐CAT‐transfected cells." (PMID 39644152, 2024). "Based on our data, we suggest that, rather than a precursor, DS and AD dyslipidemia is a consequence of AD-like Aβ and amyloid production induced by increased APP." (PMID 20049331, 2010).
pancreatic cancer (17 papers, 2011 to 2025). "We then reduced expression of APLP2 and APP by co-transfection with both siRNAs to determine if loss of both proteins would further restrict the growth of pancreatic cancer cells." (PMID 22797723, 2012). "Downregulation of APLP2 and APP expression, alone or in combination, caused a decrease in the growth of a pancreatic cancer cell line with representatively low APP C-terminal fragment expression, the S2-013 cell line." (PMID 22797723, 2012). "Recently, Aβ derived from cancer-associated fibroblasts, generated via the cleavage of APP by BACE1/2, was reported to drive neutrophil extracellular traps’ deposition in pancreatic cancer and melanoma." (PMID 38201438, 2023). "APP also increases proliferation and leads to cell size abnormalities in both lung and pancreatic cancer." (PMID 35678671, 2022). "APP is overexpressed in several types of cancer, including breast, colon, lung and pancreatic cancer, and promotes cell proliferation, invasion and migration." (PMID 35678671, 2022). "And further study figured out that the major enzyme mediating APP cleavage in pancreatic cancer is ASAM10." (PMID 35711911, 2022). "In pancreatic tumors, two distinct patterns of APP distribution were observed with regions displaying either diffuse or punctate staining that co-localized with CAFs and tumor cells consistent with Amyloid β aggregates observed in other diseases." (PMID 33514748, 2021). "Knockdown of APLP2 and APP were observed to reduce pancreatic cancer cell growth by more than 60%, and S2-013 cells treated with a β-secretase inhibitor prevented the formation of APLP2 C-terminal fragments and decreased growth." (PMID 34066808, 2021). "Coherently, it has also been observed that APP knock down in melanoma cells and in pancreatic cancer enhanced the cytotoxicity of different chemotherapeutic agents, indicating that the presence of amyloid fibrils can indeed modulate response to drugs." (PMID 33926496, 2021). "When cells that had been incubated with batimastat were treated with a recombinant form of the secreted APP fragment, growth capacity was restored, confirming that α-secretase-mediated secretion of APP contributes to pancreatic cancer cell growth." (PMID 26840089, 2016). "Pancreatic cancer cell proliferation was significantly reduced upon treatment of the cells with batimastat (which inhibits α-secretase cleavage of APP) along with gemcitabine, as compared to gemcitabine alone." (PMID 26840089, 2016). "Ultimately, the conclusion best fitting the data is that APLP2 and APP serve unique roles in the growth of pancreatic cancer cell lines." (PMID 22797723, 2012). "In both devised scenarios matching the experimental data, APLP2 and APP would have unique roles in the growth of pancreatic cancer cells." (PMID 22797723, 2012). "In this study, we found comprehensive expression of APLP2 C-terminal fragments in a panel of pancreatic cancer cell lines; however, APP C-terminal fragments were notably limited to the BxPC3 cell line." (PMID 22797723, 2012). "Fourth, down-regulation of APLP2 and/or APP impairs the growth of a pancreatic cancer cell line, and each protein likely contributes to the same growth pathway, but in a unique manner." (PMID 22797723, 2012). "Downregulation of APP by siRNA has been shown to impair the growth of BxPC3 cells, which we found have enhanced processing of APP compared to other pancreatic cancer cell lines." (PMID 22797723, 2012). "Overall, our results suggest that β-secretase, APLP2 (and notably its C-terminal cleavage fragments), and APP influence the survival of pancreatic cancer cells." (PMID 22797723, 2012). "This process has been particularly noted in the BxPC3 pancreatic cancer cell line, which has been reported to exhibit a high level of APP cleavage; however, the accompanying expression and cleavage of APLP2 in this cell line was not examined." (PMID 22797723, 2012).
pancreatic cancer (continued). "APP may promote the growth of pancreatic cancer cells through the signaling of sAPP and serve as a new therapeutic target for pancreatic cancer." (PMID 38685045, 2024). "The inhibition of BACE1/2 using different inhibitors was shown to reduce the growth and viability of pancreatic cancer cells, suggesting that the cleavage products of APP and amyloid precursor-like protein 2 (APLP2) by BACE1/2 have an important role in cancer cells’ survival and proliferation." (PMID 38201438, 2023). "Transient knock-down of APLP2 or APP reduced pancreatic cancer cell growth and viability." (PMID 26840089, 2016). "Overall, these studies suggest that APLP2 undergoes extensive modification and cleavage in pancreatic cancer cell lines, APLP2 (and APP) facilitate pancreatic cancer cell growth, and treatments that block APLP2 cleavage can diminish the growth of pancreatic cancer cells." (PMID 22797723, 2012). "Downregulation of APLP2 and/or APP in the pancreatic cancer S2-013 cell line, which displays representatively low expression of APP C-terminal fragments, decreased cell proliferation, suggesting a role for both family members in the growth of pancreatic cancer cell lines." (PMID 22797723, 2012). "Because growth inhibition was still observed when either APLP2 or APP was downregulated, APLP2 expression does not compensate for loss of APP in pancreatic cancer cell growth, and vice versa." (PMID 22797723, 2012). "Notably, tolfenamic acid, which is currently under investigation for use in pancreatic cancer, has been shown to impair expression of APP and BACE." (PMID 22797723, 2012). "Therefore, it is probable that APLP2 and APP act through the same pathway to promote the growth of pancreatic cancer cells." (PMID 22797723, 2012). "S2-013 cells transfected with APP siRNA demonstrated significantly reduced growth, compared to control siRNA, suggesting that full-length APP, rather than secretase cleavage of APP, contributes to the growth of pancreatic cancer cell lines." (PMID 22797723, 2012). "In addition to APLP2, APP was expressed in each of the pancreatic cancer cell lines." (PMID 22797723, 2012). "We determined the expression of C-terminal fragments for APP and APLP2 in our panel of pancreatic cancer cell lines by western blot analysis." (PMID 22797723, 2012). "Future investigations are required to explore the possibilities of altered APLP2 or APP regulatory mechanisms and to dissect functional identities of APLP2 and APP in pancreatic cancer growth and viability." (PMID 22797723, 2012). "Our data indicate that inhibitory therapies that target APLP2, APP and BACE may be promising for the treatment of pancreatic cancer." (PMID 22797723, 2012). "C-terminal fragments of APP were only abundantly observed in the BxPC3 cell line in our panel of pancreatic cancer cell lines, suggesting that cleavage of APLP2, rather than APP, is a consistent molecular feature of pancreatic cancer cell lines." (PMID 22797723, 2012). "In conclusion, our studies demonstrate that abundant APLP2, but not APP, C-terminal fragment expression is conserved in pancreatic cancer cell lines; however, APP and APLP2 equally regulated the growth of S2-013 pancreatic cancer cells." (PMID 22797723, 2012). "Second, C-terminal fragments are more consistently generated from APLP2 rather than APP in pancreatic cancer cell lines." (PMID 22797723, 2012). "However, the contribution of APP to the growth of pancreatic cancer cells with minimal expression of APP C-terminal fragments has not been assessed previously." (PMID 22797723, 2012). "However, our analysis has not shown a very high expression of APP C-terminal fragments in pancreatic cancer cell lines except BxPC3." (PMID 22797723, 2012).
pancreatic cancer (continued). "Finally, treatment with inhibitors of β-secretases, enzymes that cleave APLP2 or APP to release C-terminal fragments, decreased the growth and viability of the pancreatic cancer cell line S2-013 but not of a non-transformed pancreatic ductal cell line." (PMID 22797723, 2012). "Simultaneous downregulation of both APLP2 and APP did not enhance growth inhibition beyond down-regulation of APLP2 or APP alone, signifying that APLP2 and APP likely act upon the same pathway in pancreatic cancer cell growth (eliminating the scenarios in the bottom half of Table I)." (PMID 22797723, 2012).
glaucoma (16 papers, 2012 to 2025). Increased pressure in the eyeball due to obstruction of the outflow of aqueous humor. "It is also vital to note that platelets show high expression of several proteins associated with the development of glaucoma and AD, such as the amyloid precursor protein (APP) and tau protein." (PMID 35585849, 2022). "In animal models of glaucoma, the formation of Aβ peptides through cleavage of APP has been reported to be involved in the mechanisms underlying ganglion cell apoptosis." (PMID 22279552, 2012). "Based on these studies, the antagonistic effects of APP-FL and sAPPα on neuronal survival and neuroplasticity may be modulated to improve vision in diseases associated with optic nerve injury, such as glaucoma." (PMID 34768774, 2021). "Amyloid precursor protein (APP) and its cleaved products (e.g. β-amyloid) have been implicated in glaucoma pathogenesis." (PMID 31399621, 2019). "APP processing results in the accumulation of amyloid fragments in the eye, in particular in drusen, which have been associated with neurodegeneration in retinal diseases such as AMD and glaucoma." (PMID 36875133, 2023). "GAS7 may interact with other genes implicated in glaucoma pathogenesis such as MYOC, OPTN, WDR36, CAV1, nitric oxide synthase 2 (NOS2), forkhead box C1 (FOXC1), apolipoprotein E (APOE), amyloid precursor protein (APP), and clusterin (CLU)." (PMID 32545285, 2020). "Future studies could include elucidating the effects of HE3286 on APP and its processing in glaucoma and other neurodegenerative diseases." (PMID 28223915, 2017). "APP accumulation in the ONH was also reported to happen early in the microbead model in mice, with moderate IOP increase, detected at 3 days after glaucoma induction." (PMID 35409291, 2022). "In experimental-glaucoma, BMD induced ninefold and 25-fold and 36-fold and fourfold reductions in Aβ and amyloid precursor protein (APP) levels at 3 and 8 weeks, respectively, in the RGC layer, with similar results with Clo, and in vitro with all three α2ARAs." (PMID 27929541, 2016). "Moreover, it has been shown that EGCG promotes the processing of amyloid precursor protein (APP) via the nontoxic α-secretase pathway and reduces the formation of β-amyloid fibrils, which may be of particular relevance to both AD and glaucoma." (PMID 30723498, 2017).
melanoma (16 papers, 2009 to 2025). A malignant, usually aggressive tumor composed of atypical, neoplastic melanocytes. "For instance, silencing of APP in melanoma cells significantly reduced brain metastasis and metastatic burden in mice, implicating APP in promoting brain colonization." (PMID 41003874, 2025). "The LAMININ, FN1, ADGRE5, SPP1, MK, CDH1, and APP signals mainly originated from melanoma cells and were received by multiple cell types, suggesting that melanoma cells play extensive roles in the ecosystem." (PMID 41357561, 2025). "For example, human and mouse melanoma cells induce endothelial cell necroptosis, promoting tumor exudation and metastasis through amyloid precursor protein (APP) and its receptor DR6." (PMID 36065304, 2022). "Here we examined how changes in the carbohydrate moiety of gangliosides alter APP processing in human melanoma cells, neuroectoderm-derived cells." (PMID 27687691, 2016). "It was also observed upon APP downregulation in melanoma cells that there was lower expression of ABCB5 (doxorubicin-resistant transporter), which has been implicated in chemoresistance." (PMID 26840089, 2016). "Consistent with the observed reduction in ABCB5, upon APP downregulation aggressive melanoma cell lines became sensitive to chemotherapeutic drugs to which they were not previously sensitive." (PMID 26840089, 2016). "Other ARGs, including OLR1, KCNJ8, APP, POSTN, and STC1 showed significant yet heterogenous relationships with immune cells subsets, reinforcing the complexity of immune regulation in melanoma." (PMID 40943183, 2025). "Together with the conserved secretome profile, we found other proteins involved in protein aggregation, such as APP, APLP2, and APLP1, secreted by melanoma in a cell line‐specific manner." (PMID 32749065, 2020). "In this study we examined the effects of CM containing Aβ from APP over-expressing cells on three tumor cell lines, i.e., human GBM, breast cancer and mouse melanoma cells." (PMID 19480719, 2009). "In details, the authors silenced APP in melanoma cells without affecting melanoma proliferation in vitro but noticed a reduction in brain metastases formation in vivo in a melanoma mouse model." (PMID 33926496, 2021). "For this aim we subcutaneously injected B16 melanoma cells (0.25×106) in 3–4 month old APP/PS1+/− mice, modeling AD; their non-transgenic littermates (harboring the B6 genotype); and age-matched A53T α-Syn+/+ mice." (PMID 21611169, 2011). "Importantly, B16 melanoma growth rate in A53T α-Syn+/+ mice was significantly higher than the growth rates measured for the APP/PS1+/− and their non-transgenic control littermates, injected and treated in parallel." (PMID 21611169, 2011). "Therefore, the CM from APP over-expressing 7W cells decelerated proliferation of both adenocarcinoma and melanoma cells, suggesting that the inhibition was independent of tumor cell types." (PMID 19480719, 2009).